UBE2Q2P1 (UBE2Q2 pseudogene 1)
Synonyms: FLJ43276; formerly UBE2QP1
Gene: Transcribed unprocessed pseudogene on chromosome 15 (84,526,781 to 84,570,700, reverse strand). Ensembl gene ENSG00000189136.
Diseases named in the same sentence as UBE2Q2P1 in open-access papers:
UBE2Q2P1 is named in the same sentence as 1 disease in open-access papers, as found by Europe PMC text mining. Sharing a sentence is not in itself a finding about the gene and the disease.
UBE2Q2P1 shares sentences with these, for which no sentence is quoted: cervical cancer (1 paper).